DUSP6 (dual specificity phosphatase 6)
Diseases named in the same sentence as DUSP6 in open-access papers (continued):
Sharing a sentence is not in itself a finding about the gene and the disease.
Cognitive impairment (3 papers, 2020 to 2025). Abnormal cognition is characterized by deficits in thinking, reasoning, or remembering. "In summary, this study revealed that the cognitive impairment caused by Sevo is related to regulation of METTL14/DUSP6 through m6A methylation." (PMID 41175640, 2025).
colitis (3 papers, 2018 to 2024). Inflammation of the colon. "In the IL-10 knockout mouse model of spontaneous colitis, additional DUSP6 deficiency exacerbated disease symptoms, indicating a regulatory function of DUSP6, which was confirmed by increased IFNγ production from colonic and mesenteric lymph node CD4+ T cells." (PMID 31159473, 2019). "Despite, these intriguing findings, future studies are needed to demonstrate that the protective role of DUSP6 in colitis is intrinsic to CD4+ T cells." (PMID 30429852, 2018). "The role of DUSP6 in intestinal inflammation was addressed using an IL-10−/− colitis model." (PMID 30429852, 2018). "DUSP6 deletion was also shown to protect mice with dextran sulfate sodium (DSS)-induced colitis, a non-autoimmune model of inflammatory bowel disease, though the precise mechanism was not clear." (PMID 38974475, 2024).
dementia (3 papers, 2020 to 2024). Loss of intellectual abilities interfering with an individual's social and occupational functions. "The Spearman correlation coefficients showed that the downregulation of DUSP6 gene expression is correlated with increased clinical dementia rating (CDR) scores in both sexes." (PMID 39006222, 2024). "Likewise, Venn analysis of downregulated genes identified 3 genes, dual specificity phosphatase 6 (DUSP6), VGF nerve growth factor inducible (VGF), and activity regulated cytoskeleton associated protein (ARC) shared between dementia types." (PMID 32192109, 2020). "Therefore, specific DUSP6 inhibitors may prove useful in treating ischemia-induced neurodegeneration and dementia, benefitting both cardiac arrest and ischemic stroke patients." (PMID 37175394, 2023). "Importantly, decreased DUSP6 levels are correlated with an increased clinical dementia rating (CDR) in human subjects, and DUSP6 levels are additionally decreased in the 5xFAD amyloidopathy mouse model." (PMID 39006222, 2024).
diabetic nephropathy (3 papers, 2023 to 2025). "However, other studies have found that overexpression of TUG1 overexpression can alleviate kidney injury in diabetic nephropathy mice and reduce the inflammatory response and fibrosis of high glucose-stimulated HK-2 cells through the miR-145-5p/DUSP6 axis." (PMID 40755781, 2025). "Moreover, in diabetic nephropathy patients who have the highest prevalence of CKD, DUSP6 has been found to mediate protection against high glucose-induced inflammation." (PMID 37026010, 2023).
hypogonadotropic hypogonadism (3 papers, 2018 to 2026). Abnormal ovarian or testicular function due to insufficient hormonal stimulation from the hypothalamic-pituitary axis. "Additionally, congenital hypogonadotropic hypogonadism in humans affects both males and females and has been linked to missense mutations in DUSP6 and other ERK regulators." (PMID 29544468, 2018). "Variants in DUSP6 are implicated in Kallmann syndrome, a form of hypogonadotropic hypogonadism with delayed or absent onset of puberty and reduced testicular volume." (PMID 31719618, 2019).
osteoporosis (3 papers, 2021 to 2025). A condition of reduced bone mass, with decreased cortical thickness and a decrease in the number and size of the trabeculae of cancellous bone (but normal chemical composition), resulting in increased fracture incidence. "Furthermore, overexpression of DUSP6 attenuated bone loss in the ovariectomy-induced osteoporosis model." (PMID 34475393, 2021). "In recent research on osteoporosis, DUSP6 was found to be downregulated in osteoporotic bone samples with its inhibition leading to an increase in osteoclast differentiation in vitro, while its upregulation had suppressive effect on osteoclasts." (PMID 41295056, 2025). "DUSP6 expression was suppressed in human and mice osteoporosis cases and DUSP6 overexpression prevented osteoclastogenesis was confirmed in vitro experiments." (PMID 40218365, 2025). "Using bioinformatics, we identified miR-181a as a potential regulator of DUSP6 and confirmed that it was positively correlated with osteoporosis in human and mice samples." (PMID 34475393, 2021). "In this study, gene expression profile analysis and real-time polymerase chain reaction revealed that DUSP6 expression was suppressed in human and mice osteoporosis cases." (PMID 34475393, 2021). "Considering the differential mRNA expression between the osteoporosis and normal groups, we focused on the miRNAs to further explore the upstream DUSP6 regulation." (PMID 34475393, 2021). "We then established an ovariectomy (OVX)-induced osteoporosis murine model, and DUSP6 was suppressed in the osteoporosis group, as confirmed by immunohistochemistry." (PMID 34475393, 2021). "Altogether, this study demonstrated for the first time the role of miRNA-181a/DUSP6 in the progression of osteoporosis via the ERK2 and SMAD2 signaling pathway." (PMID 34475393, 2021). "Given the special effect of DUSP6 on osteoclastogenesis, along with the present findings, DUSP6 might be a novel target for treating osteoporosis or rheumatoid arthritis." (PMID 34475393, 2021). "Additional experiments using DUSP6f/f-Lyzm-cre mice could provide valuable information on the role of DUSP6 in osteoporosis progression." (PMID 34475393, 2021). "Moreover, the fluorescence intensity of DUSP6 in the (E/Z)-BCI-treated group was lower than that in the untreated osteoporosis group." (PMID 34475393, 2021). "To explore the function of DUSP6 in vivo, we established an experimental osteoporosis murine model." (PMID 34475393, 2021). "Thus, DUSP6 might be a target for treating osteoclast-related diseases, such as osteoporosis and rheumatoid arthritis." (PMID 34475393, 2021). "Some studies reported that DUSP1, DUSP2, and DUSP5 are involved in osteoclast-related diseases, such as osteoporosis and rheumatoid arthritis, but the role of DUSP6 has not been studied." (PMID 34475393, 2021). "XPR1, SLC4A2, and GNPTAB were previously reported to be related to osteoporosis, but GRAMD1B, ITGA6, and DUSP6 have never been studied with respect to any musculoskeletal-related diseases." (PMID 34475393, 2021).
triple-negative breast carcinoma (3 papers, 2019 to 2024). An invasive breast carcinoma which is negative for expression of estrogen receptor (ER), progesterone receptor (PR), and human epidermal growth factor receptor 2 (HER2). "DUSP6 (overexpressed in MCF7 and BT20 WWOXlow) is associated with brain metastasis in triple-negative breast cancer." (PMID 35290621, 2022). "Accordingly, siRNA-mediated knockdown of DUSP6 reduced HER2 and HER3 protein levels in MDA-MB-453, HCC1954, and the HER3+ triple-negative breast cancer cell line MDA-MB-468." (PMID 38886591, 2024).
Virus infection (3 papers, 2021 to 2024). "Virus infection, in particular infection with Epstein Barr virus (EBV), causes MAPKERK overactivity, which is probably mediated by downregulation of DUSP6 (MKP-3) and DUSP-8." (PMID 33948692, 2021). "MAPK/ERK hyperactivity is brought on by viral infection, specifically EBV infection, that could be mediated by DUSP-8 and DUSP-6 (MKP-3) downregulation." (PMID 39144488, 2024).
Alzheimer disease (2 papers, 2024 to 2025). A progressive, neurodegenerative disease characterized by loss of function and death of nerve cells in several areas of the brain leading to loss of cognitive function such as memory and language. "Dual specificity protein phosphatase 6 (DUSP6) was recently identified as a key hub gene in a causal VGF gene network that regulates late-onset Alzheimer’s disease (AD)." (PMID 39006222, 2024). "Examination of brain samples from patients with Alzheimer's disease indicated a substantial decrease in DUSP6 expression within the hippocampus and cortex compared to healthy individuals, accompanied by abnormal increase of ERK1/2 phosphorylation, neuronal apoptosis and so on." (PMID 41175640, 2025).
anaplastic thyroid carcinoma (2 papers, 2017 to 2025). "Consistent with the protumoural role of DUSP6 in PTC, DUSP6 silencing decreased cell viability and migration of anaplastic thyroid carcinoma FRO cells." (PMID 40943262, 2025).
autoimmune disease (2 papers, 2024 to 2026). A disorder resulting from loss of function or tissue destruction of an organ or multiple organs, arising from humoral or cellular immune responses of the individual to their own tissue constituents. "We further demonstrate a key role for IL10 in mediating the DUSP6 KO protective effect and consider DUSP6 as a potential target for therapeutic development for RA and other autoimmune diseases." (PMID 38974475, 2024). "To our knowledge, this is the first time that DUSP6 KO mice are studied in a model of autoimmune disease, and we show that these mice are significantly protected and have reduced levels of pro-inflammatory cytokines, and increased levels of IL10 and IL10-producing cells." (PMID 38974475, 2024). "Downregulation of DUSP1, DUSP3, DUSP11, and DUSP22, as well as upregulation of DUSP4, DUSP6, and DUSP23 are involved in human autoimmune diseases." (PMID 42087139, 2026).
bladder cancer (2 papers, 2022 to 2025). "Relationship between DUSP6 expression and clinicopathological features of patients with bladder cancer." (PMID 40936711, 2025). "To further confirm whether DUSP6 mediates mitophagy in bladder cancer through the mTOR pathway, we pre-treated DUSP6 knockdown cells with medium containing 1.5 μM of mTOR agonist MHY1485 for 12 hours, and observed that the level of mitophagy was decreased." (PMID 40936711, 2025). "There results indicate that the DUSP6 mediates mitophagy through mTOR pathway in bladder cancer." (PMID 40936711, 2025).
breast invasive carcinoma (2 papers, 2016 to 2024). "However, DUSP6 expression in benign breast tissue compared to invasive breast carcinomas has yet to be investigated." (PMID 26859151, 2016).
chronic kidney disease (2 papers, 2019 to 2025). Impairment of the renal function secondary to chronic kidney damage persisting for three or more months. "Another report confirmed this age associated rise in CD4+ T cell DUSP6 expression, and found that young immunosuppressed patients with end stage renal disease have DUSP6 levels comparable to elderly healthy individuals." (PMID 30941033, 2019).
cutaneous melanoma (2 papers, 2018 to 2021). A primary melanoma arising from atypical melanocytes in the skin. "DUSP6 expression in cutaneous melanoma is the highest among all cancer cell lines and the second highest among cancer tissue types, suggesting DUSP6 plays a particularly important role in cutaneous melanoma." (PMID 30577494, 2018).
diabetes (2 papers, 2009 to 2021). "Among the genes that were significantly up-regulated in diabetes were Retnla, Gjb2, Itga, Slit and Dusp6, and among the genes that were down-regulated were Krueppel-like factor 8, IGFBP, Ngfg, Foxa3, Kcnc2 and Dlp8." (PMID 19649297, 2009).
epilepsy (2 papers, 2024 to 2025). A brain disorder characterized by episodes of abnormally increased neuronal discharge resulting in transient episodes of sensory or motor neurological dysfunction, or psychic dysfunction. "The ERK/MAPK pathway, implicated in SE, seizure, and epilepsy showed early dysregulation during the acute phase, which genes such as dual-specificity phosphatase 6 (Dusp6), specific for ERK1/2, being upregulated at the 1-h time point, but then down regulated at 36 and 120 h." (PMID 39040630, 2024).
hearing loss (2 papers, 2019 to 2021). "Indeed, the inactivation of Dusp6 leads to hypoacusis that results from malformations in the middle ear and otic capsule but not in the cochlea." (PMID 30938680, 2019). "DUSP6 (Dual Specificity Phosphatase 6; chr 12q21.33) and SPRY4 (Sprouty RTK Signaling Antagonist 4; chr 5q31.1) are repressors of the FGF8/FGFR1-activated MAPK cascade and pathogenic variants were found in patients with either normosmic CHH and KS together with hearing loss." (PMID 34502334, 2021).
ischemia (2 papers, 2022 to 2023). A hypoperfusion of the BLOOD through an organ or tissue caused by a PATHOLOGIC CONSTRICTION or obstruction of its BLOOD VESSELS, or an absence of BLOOD CIRCULATION. "Taken together, Dusp6 ablation significantly reduces progressive LV damage in acute inflammatory phase while has no protective effect on the early ischemia-induced myocardial necrosis and apoptosis." (PMID 36335128, 2022).
muscular dystrophy (2 papers, 2024 to 2025). Muscular dystrophy (MD) refers to a group of more than 30 genetic diseases characterized by progressive weakness and degeneration of the skeletal muscles that control movement. "A variant in the DUSP6 gene correlated with body mass was identified in the QTL mapping data for body mass in the context of muscular dystrophy." (PMID 40218365, 2025). "Dusp6 is a genetic modifier of muscular dystrophy in Sgcg-deficient D2 mouse." (PMID 38233267, 2024).
myeloma (2 papers, 2012 to 2020). "Previous gene expression analyzes (also using Affymetrix expression arrays) in myeloma cells have identified DUSP6 as one of only three genes which were uniquely and strongly elevated in cells harboring activated N-RAS." (PMID 22784513, 2012). "Moreover, a six-gene risk score model (ZNF486, EPHA5, RP11.326C3.15, DUSP6, DUSP10, and TRIAP1) for the prognostic prediction of PI-treated myeloma patients was developed by the random survival forest variable hunting (RSF-VH) algorithm." (PMID 33344452, 2020).
ovarian tumor (2 papers, 2021 to 2023). "Moreover, HE4 has been described as a driver of immune failure in ovarian tumors by compromising cytotoxic CD8+ T cells through upregulation of self-produced dual-specificity phosphatase 6 (DUSP6)." (PMID 33917869, 2021).
Parkinson disease (2 papers, 2019 to 2022). A progressive degenerative disorder of the central nervous system characterized by loss of dopamine producing neurons in the substantia nigra and the presence of Lewy bodies in the substantia nigra and locus coeruleus. "DUSP1 and DUSP6 phosphatases also behave as molecular markers of the progression and prognosis of Parkinson’s disease (PD)." (PMID 31018603, 2019).
renal cell carcinoma (2 papers, 2022 to 2025). "DUSP6 seems to have an oncosuppressor role also in renal cell carcinoma (RCC) as it was demonstrated by Liu and colleagues." (PMID 40943262, 2025). "The MAPK phosphatase family member dual-specificity phosphatase 6 (DUSP6), may be a crucial effector for SKA1-mediated malignant progression of renal cell carcinoma based on the degree of connection between cancer cell motility and target genes, p-value, and fold change." (PMID 36462498, 2022).
thyroid (2 papers, 2017 to 2022). "DUSP5 and DUSP6 are specifically induced by the MEK-ERK pathway in the three PTC oncogenes inducible thyroid cell lines." (PMID 28910386, 2017). "DUSP6, a member of the MAPK phosphatase family, is highly expressed in PTC and plays a pro-oncogenic role in thyroid tumorigenesis by regulating the ERK1/2 pathway, cell proliferation, and invasiveness." (PMID 36077665, 2022).
thyroid tumor (2 papers, 2020 to 2023). A benign or malignant neoplasm affecting the thyroid gland. "DUSP5 and DUSP6 expression levels were higher in human thyroid tumors than in the tumor-free tissue and controls." (PMID 37964961, 2023).
/T-cell lymphoma (1 paper, 2022). "In natural killer/T-cell lymphoma, WTAP upregulated DUSP6 expression through m6A modification, inducing drug resistance." (PMID 36207306, 2022).
adenoma (1 paper, 2013). A neoplasm arising from the epithelium. "The villus, crypt and ISC preparations were subjected to bisulfite pyrosequencing of eleven specific DMRs, among them Dusp6 and Fos (containing adenoma-hypomethylated DMRs), as well as Ush1g and Vdr (containing adenoma-hypermethylated DMRs)." (PMID 23408899, 2013).
amyloid (1 paper, 2024). "Taken together, these data suggest that DUSP6 is potentially involved in the regulation of hAPP translation, Aβ peptide production, degradation, and/or amyloid plaque clearance." (PMID 39006222, 2024).
ankylosis (1 paper, 2013). Fixation and immobility of a joint. "In addition to Fgf23, R1MAb2 and vitamin D treatment similarly induced the expression of several genes, including osteocalcin (Ocn), osteoprotegerin (Opg), progressive ankylosis (Ank), dual-specificity phosphatase 6 (Dusp6), and apolipoprotein D (Apod)." (PMID 23451204, 2013).
Apert syndrome (1 paper, 2018). Apert syndrome (AS) is a frequent form of acrocephalosyndactyly, a group of inherited congenital malformation disorders, characterized by craniosynostosis, midface hypoplasia, and finger and toe anomalies and/or syndactyly. "Our quantitative analyses demonstrate that the Apert syndrome Fgfr2 P253R mutation induces changes in the expression pattern of Dusp6 and that these genetic changes are associated with significant phenotypic alterations." (PMID 30234486, 2018). "Overall, the high correlation between the shape of the limb and the Dusp6 expression domain provides further evidence that altered Fgf expression resulting from the Fgfr2 mutation is strongly associated with limb defects in Apert syndrome." (PMID 30234486, 2018). "We found evidence that limb shape and Dusp6 expression were highly associated, but it is likely that other downstream genes of the Fgf signaling pathway also contribute to the limb shape malformations associated with Apert syndrome." (PMID 30234486, 2018). "Therefore, the alteration of the Dusp6 expression pattern between E10 and E11.5, caused by the Fgfr2 mutation, will correlate with the limb dysmorphologies associated with Apert syndrome." (PMID 30234486, 2018). "Overall, the time courses showing the dynamics of limb shape and gene expression pattern changes throughout development confirmed that the Fgfr2 Apert syndrome mutation causes an aberrant overexpression of Dusp6 early in development, which could later lead to significant limb malformations." (PMID 30234486, 2018). "First, to visualize the expression pattern of a downstream target of Fgfr2, we obtained OPT scans of Fgfr2+/P253R Apert syndrome mouse embryos that had been analyzed with WMISH to reveal Dusp6 expression." (PMID 30234486, 2018). "Accordingly, the volume of the Dusp6 expression domain was significantly larger in Apert syndrome mice, even when these mice had significantly smaller limbs." (PMID 30234486, 2018).